INS (insulin)
Diseases named in the same sentence as INS in open-access papers (continued):
Sharing a sentence is not in itself a finding about the gene and the disease.
Insulin resistance (continued). "Particularly in type 2 diabetes (T2D), hyperglycemia is caused by chronically impaired insulin signaling, decreased insulin sensitivity, or insulin resistance (IR)." (PMID 37110230, 2023). "Type 2 diabetes (T2D), a serious chronic disease caused by insulin resistance and impaired insulin secretion, is a global health and wellness issue." (PMID 36771483, 2023). "This consequently reduces insulin sensitivity and causes insulin resistance, which is a key feature of metabolic syndrome." (PMID 38001499, 2023). "The results indicated that a high-fat diet caused abnormal glucose metabolism in obese mice, reduced insulin sensitivity, and induced insulin resistance in obese mice." (PMID 37686768, 2023). "In RA patients, glucocorticoid therapy has been associated with an increase in insulin resistance, a decrease in insulin sensitivity, and a higher risk of type 2 DM." (PMID 36983150, 2023). "A typical mechanism underlying insulin resistance is dysregulation of insulin signaling, such as improper phosphorylation of insulin receptor substrates." (PMID 36803098, 2023). "Insulin resistance was found to be associated with fasting insulin, HOMA index, body mass index and right ovarian volume in patients diagnosed with PCOS." (PMID 36829146, 2023). "Acromegaly is the only disease with simultaneous elevation of circulating GH, IGF1 and insulin levels, and in which insulin resistance is associated with a reduction in body fat deposits, especially liver fat." (PMID 37842314, 2023). "Sirolimus treatment disrupts the insulin signal transduction, causing insulin resistance, reducing insulin secretion, and decreasing beta-cell survival and proliferation." (PMID 37374048, 2023). "BPA treatment for 6–24 h increased the secreted protein levels of the suppressor of cytokine signaling 3, which is a negative regulator of insulin signaling and is associated with insulin resistance." (PMID 38132710, 2023). "Type 2 diabetes (T2D) is a metabolic disorder characterized by loss of pancreatic β-cell function, decreased insulin secretion and increased insulin resistance, that affects more than 537 million people worldwide." (PMID 36980190, 2023). "In turn, it has been well established that low thyroid hormone levels underlie insulin resistance, which is characterized by increased insulin secretion, in both GDM and type 2 diabetes." (PMID 37447240, 2023). "Insulin resistance is closely linked to obesity, forming a dynamic interaction that has long intrigued researchers, and the intricate cause-and-effect relationship between insulin and insulin resistance remains a subject of ongoing debate." (PMID 38068822, 2023). "Studies in PAI-1 null-allele mice have highlighted better effects on insulin and glycemic measures when mice were fed a high-fat diet, as well as protective effects against development of obesity and insulin resistance." (PMID 36674648, 2023). "In these tissues, insulin resistance is associated with impaired insulin-dependent translocation of GLUT4, resulting in decreased glucose uptake." (PMID 38053837, 2023). "Insulin resistance is associated with a disruption in the normal cyclical pattern of insulin secretion." (PMID 37446104, 2023). "First, evidence showed that the transition from NFG to prediabetes in subjects was associated with increased weight and insulin resistance and reduced endogenous insulin secretion." (PMID 36639363, 2023). "Incessant hyperglycemia, insulin resistance, and impaired insulin signaling have been reported as the major risk factors of different diabetic cardiac disorders as seen in the pathogenesis of diabetic cardiomyopathy (DCM)." (PMID 35841183, 2023). "Insulin resistance is also related to the inflammation of adipose tissue, as pro-inflammatory adipokines can cause insulin resistance by disrupting insulin signalling pathways in addition to their effect on glucose metabolism." (PMID 36014924, 2022).
Insulin resistance (continued). "An increase in iron storage also causes insulin resistance, and insulin sensitivity increases after reducing serum iron levels." (PMID 36479119, 2022). "Another study showed that vitamin D can indirectly stimulate insulin secretion and reduce the risk of insulin resistance by normalizing extracellular calcium by changing the calcium flow of cell membranes." (PMID 36352900, 2022). "Hyperglycemia associated with insulin resistance negatively affects insulin delivery to skeletal muscle and directly injures the endothelium." (PMID 35277006, 2022). "Our study shows that nonsynonymous variants in nine candidate genes are all associated with better insulin secretion adjusted for insulin resistance." (PMID 35163144, 2022). "Statins impair insulin signaling causing statin-induced insulin resistance in adipose tissue, coincident with activation of NLR family pyrin domain-containing 3 (NLRP3) inflammasome and impaired insulin-stimulated lipogenesis in adipocytes." (PMID 36558473, 2022). "Because of the significant decrease in insulin sensitivity in normal pregnancy, this predisposing initial insulin resistance is further exacerbated and, in combination with β-cell dysfunction, results in the development of GDM." (PMID 35440068, 2022). "This was associated with insulin resistance of MSCs from aged donors caused by the increase in the basal level of activation of crucial insulin-dependent intracellular effectors ERK1/2 and Akt." (PMID 36467400, 2022). "Insulin resistance attenuates the inhibitory effect of insulin on islet ɑ cells secretion and cause hyperglucagonemia, while hyperglucagonemia is an important part of the pathogenesis of insulin resistance in type 2 diabetes." (PMID 36307866, 2022). "Type 2, or non-insulin-dependent diabetes, the more common type, is characterized by increased plasma glucose levels due to insulin secretion deficiencies and insulin resistance." (PMID 35630078, 2022). "Longitudinal studies of glucose tolerance and insulin sensitivity will be required among PASC individuals to assess the distinction between insulin resistance and deficiency." (PMID 35318939, 2022). "In T2DM, excess insulin production by beta cells to compensate for insulin resistance in peripheral tissues causes high oxygen consumption, resulting in hypoxia within and around the beta cells." (PMID 36139075, 2022). "Unlike adipocyte hyperplasia that is associated with adipocyte proliferation and insulin sensitivity, adipocyte hypertrophy results in secondary complications such as hepatic steatosis and insulin resistance." (PMID 35425699, 2022). "Elevation in plasma insulin concentrations and disruptions in insulin signaling are often the repercussions of obesity and insulin resistance and constitute hallmarks of these conditions which are risk factors of NAFLD." (PMID 36364811, 2022). "Data from 13,644 adults showed that very low muscle mass is a risk factor for insulin resistance, and that higher muscle mass is associated with better insulin sensitivity because muscle is the main location of insulin-mediated glucose disposal." (PMID 36309772, 2022). "Its effect on insulin resistance has been described, and is caused by stimulated insulin secretion in the presence of high blood glucose levels." (PMID 35566198, 2022). "T2DM is triggered by insulin resistance (IR), caused by decreased glucose uptake and insulin sensitivity due to obesity, ageing, and sedentary lifestyle." (PMID 35267269, 2022). "Increased insulin resistance likely plays a central role; one night of experimental sleep restriction (4 h) in seven persons with T1D was associated with decreased peripheral insulin sensitivity, compared to normal sleep duration (7.8 h)." (PMID 35986415, 2022). "As clinical administration of olanzapine has long been proposed to cause insulin resistance and dyslipidemia, we then examined the main effects of olanzapine treatment to insulin levels." (PMID 35874808, 2022).
Insulin resistance (continued). "Although the etiology of GDM is complex, insulin resistance (IR), caused by reduced insulin sensitivity in adipose tissue, muscle and liver, is a primary feature." (PMID 36741990, 2022). "T2D is characterized by chronic hyperglycemia caused by systemic insulin resistance, impaired insulin secretion by pancreatic β-cells, and/or reduced β-cell mass." (PMID 35156417, 2022). "The idea of insulin resistance within the CNS arose from observations consistent with deficient activity of insulin within the CNS." (PMID 35884888, 2022). "Legumes enhance cardio-metabolic health by maintaining insulin sensitivity, improving lipid profiles, preventing insulin resistance, obesity, and cardiovascular risk scores and these have been well reported in the literature." (PMID 36107862, 2022). "They proposed that the initial stage of insulin resistance in adipose tissue is caused by hypoxic through inhibition of insulin signaling." (PMID 36496995, 2022). "Insulin resistance and irregular insulin production cause hyperglycemia in type 2 diabetes patients." (PMID 36557312, 2022). "As we all know, T2DM is characterized by a relative insulin deficiency and insulin resistance, while the C-peptide level is a good indicator of insulin secretion but is unable to reflect the degree of insulin resistance precisely." (PMID 36425472, 2022). "Increased production of insulin to cope with overt glucose intolerance causes higher fasting hyperinsulinemia in diabetic individuals, leading to insulin resistance." (PMID 36304231, 2022). "Any functional defect of INSR gene will directly affect the action of insulin and cause insulin resistance, thus leading to the development of T2D." (PMID 35885938, 2022). "Oxidative stress stimuli trigger dysfunction of insulin-stimulated glucose transport and the insulin signaling transduction pathway, which subsequently causes insulin resistance." (PMID 35153796, 2022). "DNA methylation of the PGC1a gene promoter modulates insulin resistance and is strongly associated with plasma fasting insulin." (PMID 35488925, 2022). "Paternally transmitted foetal DLK1 genotype affected maternal DLK1 levels that were positively associated with insulin-resistance and inversely correlated with insulin secretion during the third trimester of pregnancy." (PMID 36568069, 2022). "Relevant biological signals affected in the metabolic context of obesity and associated insulin resistance include the insulin and fatty acids." (PMID 35444566, 2022). "The regulation of peripheral insulin release prevents the development of hyperinsulinemia, which is associated with brain insulin resistance and reduced signaling." (PMID 35453527, 2022). "Obesity and insulin resistance are known to add up to this development, but beta cell and alpha cell function, respectively, have been shown to alter insulin secretion and cause a hyperglucagonemic state in adults." (PMID 36133310, 2022). "Fasting insulin levels as a marker of Insulin resistance are shown to be associated with CVD among those without T2DM." (PMID 36386371, 2022). "In a recent study, we found a strong association between increase in both fasting insulin levels as well as in degree of insulin resistance with hepatic senescence in NAFLD/NASH patients with obesity and T2D (our unpublished data)." (PMID 35872305, 2022). "Studies also revealed that people with higher levels of insulin resistance index, fasting insulin level, and estrogen are more susceptible to EC." (PMID 35752750, 2022). "Smoking leads to inadequate insulin secretion and insulin resistance via various underlying effects such as hormonal imbalance, inflammation, oxidative stress, central adiposity, and endothelial dysfunction." (PMID 35177061, 2022). "Obesity is associated with insulin resistance and impairment of insulin-induced glucose uptake by myocytes and adipocytes." (PMID 35625574, 2022).
Insulin resistance (continued). "Similar to SHR, Dahl hypertensive rats have a form of genetically induced hypertension that is completely dependent on dietary salt intake and is associated with insulin resistance and increased insulin response to an oral glucose load." (PMID 36289636, 2022). "Insulin resistance caused by metabolic, hormonal, and cytokine changes associated with the illness demands a corresponding rise in insulin output in order to maintain normal glycemia." (PMID 35673632, 2022). "Our finding of a reduced trend in l-Asp levels in type 2 diabetes-affected islets also aligns with the association of aspartate with increased insulin resistance and reduced insulin secretion." (PMID 36144204, 2022). "It mainly includes high-frequency keywords such as BMI, insulin resistance, metabolic syndrome, risk factor, leptin, insulin, and adiponectin." (PMID 36339176, 2022). "Taken together, our results show that pharmacologic activation of Sirt3 by HNK increased adipogenesis, suggesting Sirt3 inducers to be good candidates for improving insulin sensitivity and decreasing the risk of insulin resistance." (PMID 35409099, 2022). "T2DM is associated with insulin resistance, defective insulin signaling, and unrestrained gluconeogenesis." (PMID 36160451, 2022). "Intrinsic defects in GA3PDH and a loss of its responsiveness to insulin can explain the association between insulin resistance and hyperuricemia by elevation of de novo purine synthesis." (PMID 35203610, 2022). "Studies of metabolic conditions associated with insulin resistance have shown decreased Akt phosphorylation at Thr308 and Ser473 in response to insulin." (PMID 36297523, 2022). "Impaired insulin secretion and increased insulin resistance have been suggested as mechanisms underlying the development of PTDM." (PMID 35685576, 2022). "High levels of serum FFA are associated with insulin resistance through the inhibition of insulin-stimulated glucose uptake and glycogen synthesis." (PMID 36428489, 2022). "Effective insulin signaling is required for glucose homeostasis, and insulin resistance is closely associated with obesity and is a risk factor for the onset of type-2 diabetes." (PMID 35910891, 2022). "Insulin resistance can cause the partial disruption of communication between these tissues, where insulin target tissues show resistance towards the insulin signaling mechanism in spite of the initial compensation mediated by the pancreas." (PMID 36364178, 2022). "Hyperglycemia is a symptom of T2DM caused by insulin resistance and a decrease in insulin production." (PMID 35323182, 2022). "The IKKβ aspect of the NF-κB pathway in particular is linked to the development of insulin resistance; inhibition of canonical IKKβ/NF-κB signaling actually improves skeletal muscle insulin sensitivity and prevents muscle degeneration and myofiber death." (PMID 35774142, 2022). "Arsenic and molybdenum in urine were associated with lower pancreatic beta cell function, insulin resistance, lower plasma insulin levels, and higher insulin sensitivity." (PMID 36676942, 2022). "The development of insulin resistance is also associated with the direct virus influence on the insulin signaling pathway." (PMID 35054072, 2022). "Lower levels of adiponectin are a predisposing factor for insulin resistance whilehigher levels indicate increased insulin sensitivity." (PMID 37654824, 2022). "T1D results from a deficiency in insulin secretion, which leads to hyperglycemia, whereas T2D is caused by a combination of insulin resistance and an inadequate insulin-secretion response." (PMID 36552690, 2022). "Schizophrenic individuals have elevated circulating insulin levels, which corresponds to a state of insulin resistance, and are more susceptible to suffering from T2DM, and they have altered tolerance to glucose overload." (PMID 35615716, 2022).
Insulin resistance (continued). "A role of GALNT2 in modulating insulin sensitivity is also suggested by preliminary genetic studies indicating that GALNT2 variability is associated with HOMA-insulin resistance index in women with polycystic ovary syndrome." (PMID 35055114, 2022). "Type 1 DM is characterized by absolute insulin deficiency associated with pancreatic β cells destruction, while type 2 DM, which accounts for nearly 95% of individuals, is mainly due to insulin resistance (IR) and deficiency in insulin secretion." (PMID 35807588, 2022). "Insulin resistance is characterized by the loss of endogenous or exogenous insulin effect, resulting in glucose uptake and utilization disorders (James, Stockli & Birnbaum, 2021)." (PMID 36438585, 2022). "Insulin resistance occurs when a person’s tissues become resistant to insulin-induced glucose uptake and its causes among PLWH are likely multifactorial." (PMID 36225538, 2022). "Reports have suggested that signalling pathways associated with insulin and inflammation are linked with insulin resistance in poly cystic ovarian syndrome." (PMID 35152800, 2022). "Studies have demonstrated the diagnostic efficacy of METS-IR over other non-insulin-based insulin resistance indices." (PMID 35836938, 2022). "During lipid overload, increased CD36-mediated FA uptake and lipid accumulation are known to precede the development of insulin resistance and the associated loss of insulin-stimulated glucose uptake." (PMID 36361698, 2022). "In humans, plasma BAIBA concentration is inversely correlated with fasting glucose, insulin, the Homeostatic Model Assessment-Insulin Resistance, and triglycerides, i.e., BAIBA is closely associated with better metabolic profiles." (PMID 36539818, 2022). "T2DM is characterized by hyperglycemia and is caused by insulin resistance, reduced or insufficient insulin secretion, and/or improper secretion of glucagon hormones." (PMID 35936218, 2022). "HFD-fed models usually had enhanced production of systemic leptin and insulin, which was associated with leptin and insulin resistance, as well as metabolic disorder." (PMID 36558373, 2022). "Insulin resistance is caused by impaired responses to insulin signaling in peripheral tissues such as muscle, liver, and fat." (PMID 35432205, 2022). "In most previous studies, high BMI has been associated with abnormal insulin resistance, yet these data suggest that insulin secretory dysfunction also plays a crucial role in the pathogenesis of GDM in obese women." (PMID 36295825, 2022). "Hsd11b1 has been reported to be associated with glucocorticoid-induced insulin resistance and the mediation of insulin release in pancreatic islets." (PMID 35741777, 2022). "Dysfunctional insulin signaling was reported to increase oxidative stress in PD, and an animal study demonstrated that chronic insulin resistance was associated with mitochondrial disruption and dopaminergic neuronal degeneration." (PMID 35631532, 2022). "In people with T2D, plasma Mg2+ concentration was inversely associated with markers of insulin resistance; i.e., the lower Mg2+, the more insulin resistant." (PMID 36093068, 2022). "Type 2 diabetes (T2D) is mainly characterized by insulin deficiency, including insulin resistance (insulin relative deficiency) and β Cell insulin secretion decreased." (PMID 36568082, 2022). "In conclusion, the present study demonstrated that LDs in β cells were associated with insulin resistance, hyperglycemia and β cell dysfunction involving decreased mature insulin granules in type 2 diabetes." (PMID 36204103, 2022). "There is a link between hepatic steatosis and insulin resistance, and numerous rat models have been used to show that lower hepatic TG pools are linked to better insulin sensitivity." (PMID 36564752, 2022).